IGF1 (insulin like growth factor 1)
Diseases named in the same sentence as IGF1 in open-access papers (continued):
Sharing a sentence is not in itself a finding about the gene and the disease.
acromegaly (continued). "It, thus, makes sense that the normalization of serum IGF-1 levels during SSA does not necessarily imply the control of disease’s activity in peripheral tissues, which is a condition that Neggers coined as being “extra-hepatic acromegaly”." (PMID 35448486, 2022). "In addition, longitudinal imaging data from the patients with acromegaly after surgery are lacking to further investigate whether there are dynamic microstructural alteration in the cortex and white matter in acromegalic patients with decreases serum GH/IGF-1 levels." (PMID 33912457, 2021). "It is likely that GH and IGF-1 excess has a negative impact on the CV and immune system, which may contribute to the pathogenesis of CVD in patients with acromegaly." (PMID 32458292, 2020). "Furthermore, we only included consecutive treatment-naive patients, whereas others also included patients with active acromegaly despite treatment, as acromegaly treatment is known to reduce OSAS severity, even when IGF-1 levels are not normalized." (PMID 31612224, 2020). "Although patients with truly silent somatotroph adenomas will have normal preoperative GH and IGF-1 levels, other cases will be clinically apparently silent but will show nonsuppressible serum GH and elevated IGF-1 levels (whispering adenomas)." (PMID 30020466, 2019). "One AIP mutation carrier in our kindred, the proband's male cousin (III.b), who has no symptoms of acromegaly and has normal MRI, was found with slightly increased IGF-1 (1.03 × ULN), but his GH nadir on OGTT was 0.28 μg/L, and a repeated IGF-1 later was normal." (PMID 29849625, 2018). "Acromegaly was not cured by trans-sphenoidal surgery, was partially resistant to octreotide LAR and was successfully controlled by pegvisomant treatment, as assessed by IGF-1 serum measurements." (PMID 25962899, 2015). "In this case, PAS up to 60 mg every 4 weeks failed to adequately control IGF-1 levels, whereas subsequent combination therapy with PAS and PEG achieved biochemical remission and tumor stabilization, highlighting the potential role of combination strategies in aggressive acromegaly." (PMID 42314763, 2026). "Examine, in a real-world setting, whether strict normalization of modestly elevated insulin-like growth factor 1 (IGF1) results in clinical and health-related quality of life benefits in patients with acromegaly using an open-label, non-randomized, 6-month prospective interventional study." (PMID 39959623, 2025). "As screening for acromegaly is relatively simple and done with measurement of a random, non-fasting IGF-1 level that can be drawn at any time during the menstrual cycle, screening patients with PCOS for acromegaly may lessen the delay in diagnosis for reproductive-aged women with this disease." (PMID 36721176, 2023). "Hence, in patients suspicious for acromegaly, discordant GH and IGF-1 values with elevated IGF-1 levels but normal GH suppression following OGTT, may not definitively exclude the diagnosis." (PMID 33803429, 2021). "However, in patient #5, serum IGF-1 levels were increased during the time of reoperation and remained slightly elevated for four years, but serum growth hormone was at a high normal level, pituitary SRS was negative, and no clinical signs of acromegaly were noticed." (PMID 35696052, 2022).
Hyperinsulinemia (653 papers, 2005 to 2026). An increased concentration of insulin in the blood. "Epidemiologic studies show that increased risk of developing and dying from prostate cancer has been associated with elevated serum IGF-1 levels, hyperinsulinemia and metabolic syndrome." (PMID 42192996, 2026). "Given that milk protein consumption during pregnancy is linked to higher serum IGF-1 levels and postprandial hyperinsulinemia, it is likely that milk consumption shifts the IGF-1 axis to higher levels early in pregnancy." (PMID 40357063, 2025). "Key factors associated with T2D, including hyperinsulinemia and elevated levels of hepatokines such as insulin-like growth factor 1 (IGF-1), disrupt vital signaling pathways that regulate cell survival, stress responses, and apoptosis." (PMID 40127075, 2025). "Overconsumption can lead to obesity and hyperinsulinemia, resulting in overproduction of IGF-1 and consequent inflammation, increasing the risk of prostate cancer development and growth." (PMID 39954205, 2025). "In mammals, for instance, conditions like Gestational Diabetes Mellitus, characterized by fetal hyperinsulinemia and high levels of IGF-1, are associated with neurodevelopmental defects." (PMID 39422188, 2024). "The significant association between IGF-1 and hyperinsulinemia is already known, as they are closely related in intracellular signaling pathways: normal levels of IGF-1 contribute to the normal development and function of the cardiovascular system." (PMID 38920551, 2024). "In our sample, an IGF-1 level higher than 203 was found to be associated with a 9-fold increased risk of hyperinsulinemia." (PMID 38920551, 2024). "IGF-1 levels higher than 203 ng/mL and HOMA-IR values higher than 6.2 were respectively associated with a 9-times and 18-times higher risk of confirmed hyperinsulinism, compared to those with IGF levels less than 203 and HOMA-IR less than 6.2." (PMID 38920551, 2024). "Fetal hyperinsulinemia and insulin-like growth factor-I (IGF-1) have also been linked to morphological fetal heart abnormalities." (PMID 37553638, 2023). "In fact, it was already known that hyperglycaemia and hyperinsulinemia are implicated in ageing and in the development of cancer, probably due to chronic increases in insulin growth factor 1 (IGF-1)." (PMID 36983739, 2023). "On the other hand, hyperinsulinemia causes an increase in insulin growth factor (IGF)-1 and a decrease in its binding proteins." (PMID 37958310, 2023). "Cardiac hypertrophy has been found to be linked to fetal hyperinsulinemia and insulin-like growth factor I (IGF-1) deregulation." (PMID 38003449, 2023). "Hyperinsulinemia leads to elevated levels of insulin-like growth factor 1 (IGF-I), a potent pro-mitogen that can cause cancer and decrease apoptosis in cancer cells." (PMID 38020199, 2023). "Hyperinsulinemia increases IGF-1 and decreases IGFBP1/2 (that finally cause dyslipidemia or increased bioavailable estrogen), or induce β-cells failure and hyperglycemia to finally increase BC cell growth." (PMID 36849958, 2023). "Hyperinsulinemia is also associated with increased circulating levels of insulin-like growth factor-1 (IGF1), which is a potent mitogenic factor for neoplastic epithelial cells." (PMID 36297518, 2022). "Other studies found hyperinsulinemia to relate with increased risk for cancer incidence and mortality (either by a direct mechanism or by interactions with other hormones such as IGF-1)." (PMID 35921366, 2022). "The presence of hyperinsulinism in obese patients is usually associated with IR (measured as an increase in HOMA-IR) due to the increased insulin-like growth factor-1 (IGF-1) cell receptors in states of hyperinsulinemia." (PMID 35386232, 2022). "The molecular perspective suggests that elevated IGF-1, increased cytokine and estrogen levels, adipokine imbalances, and hyperinsulinemia contribute to a high risk of malignancy besides leading to poorer patient outcomes." (PMID 34751020, 2022).
Hyperinsulinemia (continued). "Obesity-linked insulin resistance and hyperinsulinemia results in elevated level of unbound IGF-1 protein in blood, with triggering of the insulin and IGF-1 receptors signal transduction pathways that eventually promotes tumor growth." (PMID 34535145, 2021). "Increased GH levels cause increased IGF1 levels, hyperinsulinemia, insulin resistance and, ultimately, hyperglycemia." (PMID 33260481, 2020). "In particular, hyperinsulinemia and elevated IGF-1 are associated with activation of pancreatic stellate cells (PSCs) that enhance production and remodeling of extracellular matrix." (PMID 32659999, 2020). "Chronic hyperinsulinemia causes the secretion of IGF-1 and lowers the production of IGF binding proteins, which consecutively heightens circulating levels of IGF." (PMID 32977765, 2020). "Hyperinsulinemia is closely associated with the increased expression of insulin-like growth factor-1 (IGF-1)." (PMID 31244777, 2019). "Hyperphagic fa/fa rats with secondary hyperinsulinemia, high IGF1/2, and large nutrient intake are therefore predisposed to activate mTORC1 and thereby to grow rapidly, including rapid glomerular growth." (PMID 31811176, 2019). "Observational studies have shown an increased CRC risk with hyperinsulinemia and elevated insulin-like growth factor-1 levels." (PMID 30157768, 2018). "Growth hormone, IGF1, and hyperinsulinemia are associated with increased risk of growth progression of some cancer types." (PMID 28316059, 2017). "Fetuin A is an endogenous inhibitor of the insulin receptor tyrosine kinase in muscle, while IGFBP1 is a modulator of insulin-like growth factor 1 (IGF-1) action associated with hyperinsulinemia and glucose intolerance." (PMID 28273805, 2017). "Hepatocarcinogenesis caused by hyperglycaemia and hyperinsulinemia through upregulating the production and bioavailability of insulin-like growth factor-1 (IGF-1) has been observed in animal models, in vitro studies and epidemiological studies." (PMID 28432278, 2017). "Hyperinsulinemia is associated with increased bioactive serum IGF-1 and can upregulate the concentration of IGF-1." (PMID 28858123, 2017). "Associations between hyperinsulinemia and increased circulating levels of IGF-1 is proposed to be involved in carcinogenesis." (PMID 27405474, 2016). "Insulin and IGF-1 are peptide hormones that stimulate proliferation of tissues and levels higher than normal (i.e. hyperinsulinemia) have been linked with carcinogenic properties in animal models." (PMID 24911052, 2014). "Despite the lack of interference with insulin binding, the use of these antibodies causes hyperglycemia and hyperinsulinemia, and can also lead to increased levels of serum IGF-1 in compensation for the reduced IGF-IR signaling." (PMID 24280167, 2013). "The complex pathophysiology of hyperinsulinemia, i.e. increased serum level of insulin-like growth factor-1 (IGF-1) and leptin and its association with the risk of PMBC has been evaluated previously and discussed extensively." (PMID 24340245, 2013). "Acute hyperinsulinemia due to consumption of high glycemic load diet would cause an increase in IGF-1/insulin-like growth factor binding protein-3 (IGFBP-3) ratio, thus enhancing the effects of IGF-1." (PMID 22898209, 2012). "Hyperinsulinemia may thus represent a novel mechanism underlying decreased muscle IGF1 sensitivity observed in obese and diabetic rats and humans." (PMID 40105689, 2025). "Despite sufficient insulin or IGF-1 levels, persistent hyperinsulinemia may cause receptor desensitization, thereby blunting anabolic signaling." (PMID 41464556, 2025). "Additionally, IR, a hallmark of metabolic syndrome, leads to hyperinsulinemia, which activates insulin-like growth factor-1 (IGF-1) receptors and initiates downstream signalling cascades that promote cell proliferation." (PMID 40485741, 2025).
Hyperinsulinemia (continued). "Indeed, IGF-1 upregulation, stimulated by hyperinsulinemia, has been discovered to be associated with a greater risk of BC in a woman cohort of the UK Biobank, suggesting IGF-1 as a target for BC prevention." (PMID 39408212, 2024). "Notably, in vitro evidence has shown that insulin resistance and hyperinsulinemia contribute to a high risk of PCa by altering the biological function of IGF-1 or IGF-2." (PMID 38243202, 2024). "Observed changes caused by hyperinsulinemia may change the local concentration of bioavailable IGF-1." (PMID 38392069, 2024). "Moreover, Lipids influences chronic inflammation associated with visceral fat and can promote hyperinsulinemia, increased IGF1, and hyperglycemia." (PMID 39493450, 2024). "Hyperinsulinemia, hyperglycemia, and hyperlipidemia are observed when circulating GH and IGF-1 levels decline, which may explain their association with steatosis." (PMID 36831184, 2023). "Moreover, overexpression of IGFBP1, a modulator of IGF1 action, is associated with hepatic ER stress, hyperinsulinemia and glucose intolerance." (PMID 37789023, 2023). "Asprosin causes hyperinsulinemia and IR which in turn could affect oxidant-antioxidant balance and increase the expression of Insulin-like growth factor 1 (IGF-1) which promotes cancer development and metastasis." (PMID 36686442, 2022). "Fasting hyperinsulinemia is a potential mediator for breast carcinogenesis, and insulin and insulin-like growth factor-1 (IGF-1) may synergistically increase BC risk." (PMID 37025252, 2022). "Hyperinsulinemia reportedly causes the failure of insulin secretion regulation, and the rapid proliferation and metastasis of cancer cells is promoted by an increase in the biological activity of insulin-like growth factor 1 (IGF-1)." (PMID 35887596, 2022). "Thus, tumor growth is enhanced in response to increased signaling by insulin and IGF-1, conferring selective advantage to cancer cells, especially in hyperinsulinemia associated conditions." (PMID 34205356, 2021). "Moreover, metabolic syndrome is known to increase cancer risk and mortality through hyperglycemia, hyperinsulinemia, insulin-like growth factor 1 (IGF-1), or an inflammatory state, and to promote cell growth and division." (PMID 34063692, 2021). "Hyperinsulinemia and high level of IGF-1 are associated with CRC progression, thus, insulin based treatment among diabetic patients might impose the risk of CRC occurrence." (PMID 31831021, 2019). "The hyperinsulinemia, associated with other growth factors like IGF-1 and IGF-2, could be responsible for hypoglycemic accidents of newborns." (PMID 30539027, 2018). "T2DM is associated with hyperinsulinemia and elevated insulin-like growth factor 1 (IGF-1)." (PMID 26901856, 2016). "First, hyperinsulinemia and a high insulin-like growth factor-1 (IGF-1) level, which are caused by increased insulin, promote cell proliferation and inhibit apoptosis, contributing to the suppression of the hepatic synthesis of the sex hormone-binding globulin." (PMID 23826253, 2013). "These speculations are also supported by studies that found an increased risk of CRC in patients with Type 2 diabetes, as hyperinsulinemia is also related to increased levels of insulin-like growth factor 1, which is known to have cancer promoting effects." (PMID 23072404, 2012). "Our study highlights the intricate interplay between insulin and IGF1 signaling in the hypothalamus and suggests that targeting IGF1 resistance may offer new therapeutic avenues for treating metabolic disorders associated with hyperinsulinemia." (PMID 40105689, 2025). "Furthermore, it has been postulated that markers of hyperinsulinemia such as IGF-1 and C-peptide may be correlated with an increased risk of CRC." (PMID 34638601, 2021).
Hyperinsulinemia (continued). "Usually, diabetic patients have hyperinsulinemia and are associated with reduced insulin sensitivity and compensatory hyperinsulinemia as well as an increased insulin-like growth factor (IGF)-1 level, which may stimulate cell proliferation in pancreas, colon, breast, and other organs." (PMID 26541196, 2015). "Additionally, changes in the endocrine and metabolic microenvironments of obese patients lead to compensatory hyperinsulinemia and increased levels of bioavailable insulin-like growth factor 1, both of which have been linked to the promotion of carcinogenesis and the inhibition of apoptosis." (PMID 25184215, 2014). "Diabetic individuals normally have hyperinsulinemia and are associated with reduced insulin sensitivity and compensatory hyperinsulinemia as well as increased insulin-like growth factor (IGF)-1 levels, which may stimulate cell proliferation in liver, pancreas, colon, ovary, breast, and other areas." (PMID 24884617, 2014). "Hyperinsulinemia and IGF‐1 also amplify the effect of LH on granulosa cells, stimulating by ricochet, early differentiation of these cells, follicular growth arrest, anovulation, cyst formation, and follicular atresia." (PMID 41532033, 2026). "It has also been theorized that prolonged hyperinsulinemia, hyperglycemia, cytokine over‐secretion and upregulation of IGF‐1 favors malignant transformation of cells." (PMID 41521805, 2026). "Conversely, omega-3 fatty acids, found in fatty fish and flaxseeds, exhibit anti-inflammatory and insulin-sensitizing effects, counteracting the pro-cancer effects of hyperinsulinemia and IGF-1 signaling." (PMID 40428567, 2025). "Insulin pretreatment essentially abrogated the ability of IGF1 to regulate Atf4, Agrp, and Pomc, suggesting that hyperinsulinemia induced IGF1 resistance in hypothalamic neurons." (PMID 40105689, 2025). "The key drivers are hyperinsulinemia and increased IGF-1 bioavailability, activating the PI3K/Akt and MAPK pathways, along with interactions with estrogen signaling." (PMID 41002547, 2025). "In our study, we showed that hyperinsulinemia is a novel mechanism that contributed to the development of IGF1 resistance." (PMID 40105689, 2025). "Diets rich in high glycemic index carbohydrates give rise to hyperglycemia, resulting in reactive hyperinsulinemia and increased insulin‐like growth factor‐1 (IGF‐1)." (PMID 39760168, 2025). "Hyperinsulinemia explains PCOS pathogenesis because insulinemia enhances steroidogenesis via its synergism with insulin-like growth factor-1 (IGF-1) in the pituitary gland." (PMID 41509115, 2025). "In the setting of liver injury, hyperinsulinemia is influenced by elevated levels of glucagon, growth hormone, insulin-like growth factor 1 (IGF-1), free fatty acids (FFAs), and proinflammatory cytokines." (PMID 41462693, 2025). "Chronic hyperinsulinemia promotes the availability of IGF-1 by decreasing the expression of IGF-binding proteins, which would otherwise sequester IGF-1, leading to the inhibition of cellular proliferation and promoting apoptosis." (PMID 39940387, 2025). "Hyperinsulinemia, a hallmark of T2DM, directly exerts mitogenic effects and enhances IGF-1 bioactivity, activating PI3K/Akt and MAPK pathways to inhibit apoptosis and stimulate cell proliferation, thereby increasing cancer risk." (PMID 40597094, 2025). "Proposed mechanisms include chronic hyperinsulinemia and insulin-like growth factor-1 (IGF-1) signalling, low-grade systemic inflammation, and shared lifestyle risk factors." (PMID 41149069, 2025). "Long-standing T2DM increases carcinogenic signaling through chronic hyperinsulinemia and the insulin-like growth factor-1 (IGF-1) pathway." (PMID 41597354, 2025). "The proband’s inadequate reaction to metformin treatment and the existence of endocrine issues, like hyperinsulinemia and increased IGF-1, reinforce the necessity for genotype-informed treatment strategies." (PMID 40428329, 2025).